NES (nestin)
Diseases named in the same sentence as NES in open-access papers (continued):
Sharing a sentence is not in itself a finding about the gene and the disease.
lung carcinoma (continued). "Finally, nestin is known to play an important role in various aspects related to lung cancer." (PMID 34943921, 2021). "Moreover, Nestin might become a potential treatment target because knockdown of Nestin demonstrated reduced cell motility in several different carcinomas, including prostate, colorectal-, nasopharyngeal- and lung carcinoma." (PMID 30819139, 2019). "However, the specific function of nestin in invasive and metastatic behavior of lung cancer cells remains unclear." (PMID 24498263, 2014). "For lung cancer, ALDH, CD44, Oct4, c-kit, and Nestin were shown to be some of the most frequently observed CSCs markers which promote tumor development." (PMID 37233697, 2023). "Thus, nestin may serve as a prognostic factor and therapeutic target in lung cancer." (PMID 34943921, 2021). "Several studies have presented evidence that nestin is involved in the molecular processes that lead to the presentation of EMT in different types of cancer, including lung cancer." (PMID 34943921, 2021). "The relationships established here suggest that positive/high nestin can be used as an added factor in determining TNM stage and judging cancer malignancy, especially for lung cancer." (PMID 26015397, 2015). "In addition, our work also firstly studied the biological relationship between nestin high expression and malignant features of NSCLC using RNA knockdown techniques, cell cycle analysis, and evaluation of a series of cell cycle-associated proteins on lung cancer cell line models." (PMID 24498263, 2014). "For instance, NESTIN relies on its own ESGE motif (amino acids 1412–1422) to competitively bind KEAP1 and promote NRF2 protein upregulation, contributing to malignant progression in non‐small cell lung cancer." (PMID 40583858, 2025). "Furthermore, super-resolution structured illumination microscopy (SIM) revealed that Nestin and lamin A/C co-localized beneath the INM of lung cancer cells." (PMID 30190500, 2018). "This analysis provided evidence of an association between positive/high nestin and median/advanced cancer stage in lung cancer, demonstrating a significant main effect of positive/high nestin versus negative/low nestin." (PMID 26015397, 2015).
ischemic stroke (22 papers, 2010 to 2025). A stroke disorder caused by obstruction of blood flow to the brain, due to thrombotic (local blood clot formation) or embolic (due to a blood clot or other material traveling from another site) event. "Following ischemic stroke in the studied mice, Nestin expression was further increased in the ipsilateral side of the SVZ, indicating that ischemia activated endogenous NSPCs in the SVZ." (PMID 34884811, 2021). "It was demonstrated that ischemic stroke increased Nestin+ cells in SVZ and DCX+/DAPI in both SVZ and DG (p < 0.01)." (PMID 34220506, 2021). "In an investigation of the localization of GFP+ cells in Nestin-GFP mice (CB-17 background) following ischemic stroke, GFP+ cells were strongly expressed in the SVZ of sham-operated mice." (PMID 34884811, 2021). "Increased nestin expression following ischemic stroke was reported in several investigations, and it was suggested that nestin‐positive cells induced by MCAO eventually shifted toward reactive astrocytes." (PMID 32281225, 2020). "Therefore, mice were subjected to ischemic stroke, and mCherry-labeled human MSCs (h-MSCs) were transplanted around the injured sites of nestin–GFP transgenic mice." (PMID 38891071, 2024). "In this study, using bone marrow-derived human MSCs (h-MSCs), we transplanted mCherry-labeled h-MSCs into nestin–GFP transgenic (TG) mice after ischemic stroke and investigated whether MSC transplantation activates endogenous iNSPCs." (PMID 38891071, 2024). "For instance, we previously demonstrated that nestin+ iNSPCs could be obtained from MCA areas of adult mouse cortex following ischemic stroke." (PMID 38534363, 2024). "For instance, Tregs removal reduced the number of Nestin+ cells after ischemic stroke." (PMID 26441532, 2015). "In addition, we have previously shown that nestin+ NSPCs activated after ischemic stroke could differentiate into neurons and glia at peri-ischemic areas, but not within ischemic areas." (PMID 32492968, 2020). "Thus, we next examined whether PDGFRβ+ PCs express the stem cell marker nestin following ischemic stroke." (PMID 26952098, 2016). "A recent study in a rat model of ischaemic stroke also found NECs in the perivascular spaces of the organizing lesion, distinct from nestin-expressing endothelial cells with speculation that NECs might arise from pericyte/precursor type cells nurtured in the perivascular niche." (PMID 24666402, 2014). "We clearly demonstrate that a spontaneous functional recovery is coincided by significantly higher expression of nestin, p-Akt, TGF-β and activation of ERK1/2 in ischemic regions following ischemic stroke in female rats." (PMID 35413803, 2022). "Under pathological conditions, such as after ischemic stroke, SVZ-derived NSPCs that express the NSPC marker Nestin are activated and migrate toward the ischemic areas." (PMID 34884811, 2021). "To further investigate the therapeutic mechanism of PE, we detected the expression of proliferation markers (Nestin and Ki-67) and apoptosis index (TUNEL) in the entorhinal cortex after ischemic stroke." (PMID 29167635, 2017). "However, although Nestin+ NSPCs in the SVZ of Nestin-GFP mice (CB-17 background) migrated toward injured regions after ischemic stroke, they did not likely reach the ischemic areas of the cortex." (PMID 34884811, 2021). "Furthermore, the immunohistochemistry staining of DCX/BrdU and Sox2/Nestin showed As IV could promote hippocampal neurogenesis and NSC proliferation after ischemic stroke, as well as in vitro." (PMID 32317974, 2020). "Therefore, Nestin-GFP mice (CB-17 background) could be used to investigate the precise roles of NSPCs and the NSPC-related mechanism of neurogenesis over long periods after ischemic stroke." (PMID 34884811, 2021).
Cerebral ischemia (20 papers, 2007 to 2024). Restriction of arterial blood supply to the brain associated with insufficient oxygenation to support the metabolic requirements of the tissue. "Furthermore, cerebral ischemia is associated with a marked acute and chronic inflammatory response, events that may significantly affect nestin signal and/or affect its cellular expression patterns." (PMID 28253906, 2017). "The presence of GFAP/Nestin+ cells suggests that cerebral ischemia induces developmental phenotypes with differentiation potential and changes the direction of differentiation within neuroglia cell populations." (PMID 39090706, 2024). "We have previously reported that the capillaries of the corpus callosum of the aged brain are the major source of proliferating, neuroepithelial, nestin-positive cells shortly after cerebral ischemia." (PMID 34382128, 2022). "After brain ischemia, nestin is expressed in astroglia and some neurons whereas, for endothelial, ependymal, and progenitor cells, the expression is seen under normal conditions." (PMID 35250819, 2022). "The upregulation of nestin in reactive astroglia has been observed in several diseases, e.g., cerebral ischemia, hippocampal excitotoxicity lesions, traumatic brain injury, and after MPTP (1-methyl-4-phenyl-1,2,3,6-tetrahydropyridine) exposure." (PMID 33078273, 2021). "In summary, our results suggest that neuroinflammatory conditions such as brain ischemia and innate immune challenge strongly up-regulate nestin signals in the brain of living animals." (PMID 28253906, 2017). "We conclude that focal brain ischemia by CD induces reactive gliosis with profound changes in the astroglial phenotype, including the expression of the immature glial marker nestin." (PMID 27313509, 2016). "Nestin, a marker of reactive astrocytes, was reported to be highly expressed in astrocytes after focal cerebral ischemia injury." (PMID 26729092, 2015). "To study the role of Smad1 in cerebral ischemia, we generated Smad1 conditional knockout mice (cKO) with Smad1 ablation in all neural cells in the CNS (Smad1fl/-; Nestin-Cre)." (PMID 26317208, 2015). "This study provides an alternative method to apply hGal1 the treatment of brain ischemia with transplantation of hNSPCs or alternative cells sources such as Nestin-expressing hair follicle stem cells." (PMID 21951913, 2011). "Nestin expression in the adult nervous system has been detected in a number of pathological conditions including cerebral ischemia., and traumatic brain injury." (PMID 18053121, 2007). "Next, to assess whether these proliferating cells were indeed NSCs, double labelling of BrdU and nestin (a phenotypic marker of stem cell) was performed 7 d after cerebral ischemia." (PMID 35146924, 2022). "EA at 2 Hz may decrease nestin immunoreactive cells and Ki67 in rats after cerebral ischemia/reperfusion." (PMID 30618558, 2018). "In addition, 2 Hz EA may elevate the number of GFAP immunoreactive cells and decrease nestin immunoreactive cells and Ki67 in rats after cerebral ischemia/reperfusion." (PMID 30618558, 2018). "BrdU+/Nestin+ and BrdU+/DCX+ cells are located in different but overlapping regions, indicating that cerebral ischemia stimulated obvious proliferation of endogenous neuroblasts." (PMID 39090706, 2024). "In the striatum, we have shown that relative expression of Nt‐3, Nestin, β‐actin, Tnfα, Il‐1β, Il‐6, and Il‐10 increased whereas expression of Bdnf, Gdnf, Vegf, and β‐III tubulin decreased after cerebral ischemia." (PMID 32281225, 2020). "After cerebral ischemia, ALK5 colocalized with Nestin (neural stem cell marker) and colocalized with DCX (neuroblast and immature neuron marker)." (PMID 31043581, 2019). "Here, we demonstrate that the nestin+-cell-specific AHRcKO and the pharmacological inhibition of AHR protect sensorimotor and memory deficits against acute cerebral ischemia and exert regulatory effects on anti-inflammation and adult neurogenesis." (PMID 31606043, 2019).
Cerebral ischemia (continued). "Salidroside was found to increase numbers of BrdU+/Nestin+/DCX+ cells in SVZ region, suggesting that salidroside may promote neuroblast proliferation after cerebral ischemia." (PMID 39090706, 2024). "Although there are no previous reports investigating the effect of MH upon nestin+ cells in adult focal cerebral ischemia/reperfusion injury, MH has been reported to enhance endogenous neurogenesis in adult global cerebral ischemia/reperfusion injury." (PMID 29312600, 2017). "Nestin is expressed by glial progenitors and also by reactive astrocytes induced by brain ischemia, but it is not expressed after peripheral LPS administration." (PMID 27313509, 2016). "In sham group, almost few BrdU/Nestin and BrdU/DCX were found in DG, however, both the numbers of BrdU/Nestin and BrdU/DCX were remarkably increased in damaged DG zone of ME rats, demonstrating that the proliferation and migration of NSC/NPC were triggered in response to cerebral ischemia." (PMID 35770087, 2022). "Besides, both the double-positive cells of BrdU/Nestin and BrdU/DCX in PNS 120 mg/kg group were significantly upregulated compared with ME rats, showing that PNS owned the ability to promote NSC/NPC proliferation and migration after cerebral ischemia." (PMID 35770087, 2022).
Anxiety (19 papers, 2015 to 2026). Intense feelings of nervousness, tension, or panic often arise in response to interpersonal stresses. "To directly investigate the link between NSCs reduction and the development of pain-associated anxiety, we used Nestin-CreER:ROSA-DTA mice to ablate Nestin-positive cells by treating the mice with Tamoxifen (TAM) for five successive days before pain-induction." (PMID 30197587, 2018). "Moreover, most patients harboring potential disease-causing variants in SLITRK2 are anxious, whereas Nestin-Slitrk2 mice appeared to exhibit reduced anxiety-like behavior in the elevated plus-maze tests." (PMID 35840571, 2022). "We created brain-specific Selenop knockout (bSelenop-/-) mice by mating Selenop-flox and Nestin-Cre mice and conducted behavior tests for anxiety-like behavior and spatial memory under both a standard (STD) and high-fat, high-sucrose diet (HFHSD) conditions." (PMID 41612851, 2026). "One of the first studies using Nestin-Cre mice targeted the glucocorticoid receptor and found the Nestin-Cre mice to be smaller than the control mice, and to exhibit lower anxiety responses." (PMID 37508396, 2023). "Higher anxiety thresholds and smaller body sizes are consistently reported in Nestin-Cre transgenic mice." (PMID 37508396, 2023). "Brain-specific deletion of Foxo1 driven by the Nestin promoter results in increased anxiety in a forced swim test, contrary to the reduced anxiety in Foxo3-deficient mice." (PMID 34727995, 2021). "By examining the morphology of Nestin-positive cells and incorporation of BrdU, we demonstrated a rapid decrease of active NSCs which was followed the appearance of anxiety behaviors, in the vDG of mice suffering chronic neuropathic pain." (PMID 30197587, 2018). "Detailed behavioural analysis of the resulting Nestin-Cre-Lpd knockout mouse line revealed a specific behavioural phenotype characterised by hyperactivity and increased anxiety." (PMID 28710397, 2017). "Paradoxically, neurogenesis ablation in the nestin-inducible Bax transgenic mouse increases baseline anxiety-related behaviors." (PMID 26795203, 2016). "The Nestin-Cre driver mouse line has mild hypopituitarism, reduced body weight, a metabolic phenotype and reduced anxiety." (PMID 26275221, 2015). "Consistent with the observations in Nestin-Cre Utx cKO mice, these Emx1-Cre Utx cKO mice also displayed anxiety-like behaviors as indicated by decreased entry into the center zone in the open field test, decreased entries, and time spent in the light box in the light-dark box test." (PMID 28970783, 2017). "Therefore, it is reasonable to speculate that increased self‐grooming will result in less anxiety in Nestin‐Pax2 mice." (PMID 37786962, 2024). "However, Nestin-Slitrk2 mice exhibited reduced anxiety-like behavior, as evidenced by increased time spent in open arms (with a similar number of entries into each open arm) in the elevated plus-maze test, without a change in time spent in the light compartment in the light-dark test." (PMID 35840571, 2022). "Furthermore, a recent study has shown that male GHRH-/- mice have reduced anxiety, indicating that activation of hypothalamic GH receptors might also be responsible for the behavioural phenotype in Nestin-Cre mice." (PMID 26275221, 2015). "Nestin;BRAFKE/+ mice showed comparable basal locomotive activity, anxiety-like behavior, and sociability." (PMID 39964758, 2025). "Nestin-NXN-/- mice were healthy and behaved normally in behavioral tests of anxiety, activity and sociability." (PMID 34198070, 2021). "Hence, low exploratory behavior of Nestin-NXN-/- was not caused by anxiety." (PMID 34198070, 2021). "We found that repeated experience of aggression increased several parameters of anxiety-driven behavior in the winners of the C57BL/6J, Nestin-GFP, and Nestin-GFPhet lines." (PMID 26648838, 2015).
Anxiety (continued). "Independent of sex, we observed for all Nestin-Cre-Lpd KO mice that latency to enter this area in the first place was noticeably longer, further suggesting increased anxiety." (PMID 28710397, 2017). "Induced-deletion of Bax in nestin-expressing cells increased hippocampal neurogenesis and had no influence on baseline anxiety and depressive-like behaviors." (PMID 26795203, 2016). "Moreover, neurogenesis ablation model using nestin-inducible TK transgenic mouse fails to show baseline anxiety-like behaviors." (PMID 26795203, 2016). "However, other studies show that ablation of neurogenesis (via the same or distinct inducible ablation techniques, e.g. irradiation, Nestin-inducible Bax mice, Nestin-tk mice) does not result in depressive- and anxiety-like behavior." (PMID 26795203, 2016). "In Nestin-CreER:ROSA-DTA mice, the NSCs and behavior were analyzed at 10 dpi when most of the SNI-treated WT mice do not show anxiety." (PMID 30197587, 2018).